IL6 (interleukin 6)
Diseases named in the same sentence as IL6 in open-access papers (continued):
Sharing a sentence is not in itself a finding about the gene and the disease.
breast cancer (continued). "Therefore, taking into account the dramatic role that this transcription factor plays in breast cancer progression, it was indubitable the significant participation of IL-6 in the development of this illness." (PMID 35163731, 2022). "In addition, decrease in saliva cortisol and IL6 has been reported among recovering patients with breast cancer after up to one year attending the MBSR program." (PMID 36510201, 2022). "In addition, we revealed that TAM-stimulated DNMT1 transcriptional expression via the IL-6-pSTAT3-ZEB1-DNMT1 axis is necessary for TAMs to promote breast cancer metastasis in the tumour microenvironment." (PMID 36273188, 2022). "Since TAM derived IL-6 was found to have a role in breast CSC enrichment, it prompted us to examine whether IL-6 alone can enhance CSCs enrichment in breast cancer cells." (PMID 35300689, 2022). "Similarly, it was reported that high level of serum IL-6 secreted by metastatic breast cancer cells were correlated with poor survival." (PMID 35924148, 2022). "Also, IL6 is secreted by CAAs and was observed to promote cancer progression when adipocytes were co-cultured with breast cancer cells." (PMID 36114508, 2022). "Similarly, IL6 also has implications in inducing epithelial–mesenchymal transitions and increasing the breast cancer stem cell population." (PMID 35159385, 2022). "Recently, it has been described that IL6 from endothelial origin acts as a paracrine factor upon MDA-MB-231 breast cancer cells, inducing VM formation, warranting further studies on calcitriol effects upon inflammatory cytokines in co-cultures of TNBC and endothelial cells." (PMID 35887002, 2022). "Since IL-1β has been described as an inducer of IL-6 expression in colon and breast cancer cells, we reasoned that IL-1β could trigger IL-6 production by Caco-2 cells." (PMID 35326545, 2022). "Similarly, miR-25-3p in breast cancer-derived EVs binding with TLR7/8 increases the expression of IL-6 and phosphorylated NF-κB." (PMID 36405712, 2022). "In summary, IL-6 signaling pathway may be potential treatment target for breast cancer patients in the future." (PMID 35924148, 2022). "Moreover, there are many studies recognizing IL6 as a key cytokine in progressive breast cancer, confirming that high levels of IL6 are related to poor breast cancer prognoses and showcasing its therapeutic significance in treating cancer patients." (PMID 35294447, 2022). "Furthermore, IL-6 is upregulated in sera of patients with advanced stages of breast cancer and in patients presenting with metastases." (PMID 35371975, 2022). "Moreover, IL-6 has also been reported to correlate with therapeutic resistance in breast cancer patients highlighting the IL-6/JAK/STAT3 pathway as an important prognostic marker in breast cancer progression, chemoresistance, and metastatic formation." (PMID 35371975, 2022). "Prognositc value of IL-6 in different types of breast cancers." (PMID 35924148, 2022). "Moreover, the expression level of IL-6 was higher in aggressive tumors with multi-drug resistance and is negatively related to the expression of estrogen receptor in breast cancer patients." (PMID 35924148, 2022). "Experimental results demonstrates that IL-6 pathway targeted drugs may have additional benefit in HER2+ breast cancer." (PMID 35924148, 2022). "In addition, IL-6 promoted breast cancer progression through the induction of the epithelial to mesenchymal transition." (PMID 35406622, 2022). "NF-κB promotes an IL-6 feed-forward inflammatory loop, whereas interruption of IL-6/NF-κB signaling may counteract IL-6-induced breast cancer chemoresistance and requires further investigation." (PMID 35371975, 2022). "This study identified ORAI1 as a regulator of PTGS2 and IL6 expressions in basal breast cancer." (PMID 35682546, 2022).
breast cancer (continued). "Most importantly, our data demonstrate that CM of 4T1 cells could induce IL-6 expression in mouse peritoneal macrophage suggesting that breast cancer cell can activate and enhance IL-6 expression in normal macrophages." (PMID 35300689, 2022). "The combination of soluble breast adipocyte-derived leptin, insulin, IL-6, and TNF-α were inducers of the release of angiogenic mediators in macrophages, representing a potential mechanism for the enhanced risk of breast cancer progression in obese individuals." (PMID 35701840, 2022). "Administration of oncolytic measles virus expressing secretory HP-NAP improved the survival of the mice with metastatic breast cancer and increase the level of pro-inflammatory cytokines, including IL-12/23, TNF-α, and IL-6, in pleural fluids of mice with pleural metastasis of breast cancer." (PMID 36613542, 2022). "Thus, in order to delineate the signalling mechanism involved in breast cancer cell mediated expression of IL-6 in activated macrophages, we checked the effect of CM of breast cancer cells on phosphorylation of p38 in macrophages." (PMID 35300689, 2022). "IL-6 was reported to mediate crosstalk between preadipocytes and breast ductal carcinoma in situ cells which may lead to progression of early-stage breast cancer." (PMID 35924148, 2022). "Specifically, the rs1800795 SNP in IL-6 is associated with an increased risk of breast cancer metastasis, irrespective of ER status." (PMID 35371975, 2022). "Indeed, IL-6 and IDO have been linked to poor treatment outcomes, tumor recurrence, and aggressive tumor progression in breast cancer, nasopharyngeal carcinoma, and prostate cancer patients." (PMID 36405719, 2022). "Conditioned medium was extracted from the breast cancer compartment in the end of each experiment and screened for proteins that could be relevant for our model, e.g. IL-6 and monocyte chemoattractant protein 1 (MCP-1)." (PMID 35243294, 2022). "Interestingly, IL-6 and MIP-1α were already implicated in the progression of breast cancer bone metastasis and osteoclastogenesis." (PMID 35243294, 2022). "Moreover, analysis of the gene expression datasets of breast cancer brain metastasis patients revealed associations of TLR1 and IL6 with poor overall survival." (PMID 36224342, 2022). "Targeting the IL-6 cytokine family/JAK/STAT-3 pathway may be a fruitful approach for early adjuvant breast cancer therapy and/or for preventing aggressive development of metastasis in secondary sites." (PMID 35163731, 2022). "In addition to breast cancer bone metastases, recent functional studies have demonstrated IL-6 to promote lung metastases in breast cancer in vivo." (PMID 35371975, 2022). "Further, expression of IL-6 receptor could have been examined in breast cancer cells for more conclusive demonstration of TAM derived IL-6 mediated activation of STAT-3 pathway in breast cancer cells." (PMID 35300689, 2022). "Activation of TGFβ1 or interleukin-8 (IL-8) and interleukin-6 (IL-6) secretion could be activated upon stromal injuries induced in the bone marrow and therefore reactivate dormant breast cancer cells." (PMID 36430404, 2022). "Whether IL-6 enhances or inhibits breast cancer cell proliferation in vitro remained controversial for several years." (PMID 35371975, 2022). "Moreover, MCTS1 has been shown to exert oncogenic effects on breast cancer progression by affecting multiple cancer-related signaling pathways, including modulation of c-Myc translation, IL-6/IL-6R signaling pathway, and Src/p190B signaling pathway." (PMID 35295953, 2022). "Previous studies using in vitro and mouse xenograft models revealed that bone marrow MSCs can accelerate tumor growth by increasing the self-renewal capacity (number) of breast cancer stem cells (CSCs), and this effect depends on the regulation of the intercellular IL-6/CXCL7 cytokine network." (PMID 35837284, 2022).
breast cancer (continued). "Interestingly, breast cancer cells can upregulate OPG in BSFs in an IL-6-dependent manner through the IL-6/STAT3 pathway." (PMID 36359766, 2022). "Overall, these data suggested that breast cancer induces IL-6 expression in TAMs." (PMID 35300689, 2022). "Besides, conditioned media from metastatic breast cancer cell also reportedly induced the expression and secretion of inflammatory cytokines including interleukin (IL)-6, IL-8, monocyte chemoattractant protein (MCP)-1 in osteoblasts." (PMID 35513484, 2022). "Consistently, differential expression of IL-6 transcripts was observed across breast cancer lines." (PMID 36289222, 2022). "ChIP data using c-Jun antibody exhibited that CM of 4T1 significantly enhanced binding of AP-1 on IL-6 promoter in RAW264.7 cells suggesting that breast cancer cell-derived CM can promote transcriptional activation of IL-6 in macrophages by inducing p38 mediated AP-1 binding on IL-6 promoter." (PMID 35300689, 2022). "Consequently, many IL-6-pathway-targeted therapies have been developed and evaluated for breast cancer." (PMID 35371975, 2022). "Thus, our results indicate that soluble factor derived from breast cancer cells can upregulate the expression of IL-6 in TAMs via p38 pathway through AP-1 mediated transcriptional regulation in TAMs." (PMID 35300689, 2022). "The experimental analysis of this study showed that serum IL-6, IL-17 and VEGF levels are closely associated with the development, progression and invasion of breast cancer and can be used as monitoring indicators for clinical prognosis and efficacy assessment." (PMID 36531035, 2022). "In addition, PADI2-mediated citrullination of histone H3 Arg26 (H3R26) has also been shown to promote the transcriptional activation of estrogen receptor α (ERα) target genes in breast cancer and of interleukin 6 (IL-6) in multiple myeloma." (PMID 35706669, 2022). "This review covers the current biological understanding of the IL-6 signaling pathway and its impact on breast cancer metastasis, as well as, therapeutic interventions that target components of the IL-6 pathway including: IL-6, IL-6Rα, gp130 receptor, JAKs, and STAT3." (PMID 35371975, 2022). "We, therefore, next examined whether FOXO1 regulated breast cancer stemness through modulating the expression of IL6 and ALHD1." (PMID 35637961, 2022). "Adipose stromal cells with plasticity could secrete IL-6 to promote migration and invasion of breast cancer cells, which could be mediated by cofilin-1 dependent pathway." (PMID 35701840, 2022). "However, concordant with our data, steady state IL-6 levels in HER2pos breast cancer cell lines were low." (PMID 35565421, 2022). "MDSCs also endow stemness to breast cancer cells via IL-6/STAT3 and NO/Notch crosstalk signaling." (PMID 35805056, 2022). "Recently, it was found that tumor exosome-derived miR-9 and miR-181a promote the formation of IL-6-high-expressing early myeloid-derived suppressor cells in breast cancer by suppressing key regulators, including SOCS3 and PIAS3, in the negative feedback circuit of the JAK/STAT signaling pathway." (PMID 35242126, 2022). "It was suggested that the cell-cell and cell-substrate dyshesion phenotype produced by IL-6 might contribute to an increased metastatic potential of breast cancer." (PMID 35406728, 2022). "Downregulation of IL-6 was related to the better response to breast cancer therapy." (PMID 35924148, 2022). "Thus, our results depicted that TAM derived IL-6 have the ability to induce angiogenesis and IL-6 alone is sufficient to induce angiogenesis in breast cancer." (PMID 35300689, 2022). "TAM derived IL-6 influences breast cancer cell migration and angiogenesis." (PMID 35300689, 2022). "Thus, our data demonstrates that TAM derived IL-6 mediates STAT-3 dependent enrichment of CSCs in breast cancer." (PMID 35300689, 2022). "To examine whether TAM derived IL-6 can promote angiogenesis in breast cancer, we performed HUVECs tube formation assay." (PMID 35300689, 2022).
breast cancer (continued). "Moreover, we establish that TAM derived IL-6 promotes metastasis, angiogenesis and tumor growth in breast cancer by in vitro and in vivo studies." (PMID 35300689, 2022). "Our previous study demonstrated that overexpression of BQ could enhance STAT3 signaling by up-regulating the expression of IL-6 to modulate tamoxifen resistance in breast cancer." (PMID 35054486, 2022). "In metastatic lesions of breast cancer patients, upregulated IL-6 was identified which may lead to chemotherapy resistance such as paclitaxel." (PMID 35924148, 2022). "utilized a microfluidic chip, which mimics the breast cancer microenvironment and breast metastatic phenotypes in vitro, and found that IL-6-treated breast cancer cells successfully invaded into blood and lymph vessels mimicking breast cancer lymphatic metastasis in vitro." (PMID 35371975, 2022). "In addition, several cross-sectional studies have shown higher circulating IL-6 concentrations in breast cancer patients than in controls, as often reported for cancer patients overall." (PMID 35948877, 2022). "Furthermore, evidence has shown that GPX8 maintains an aggressive breast cancer phenotype by regulating the interleukin 6 (IL-6)/JAK/STAT3 signaling pathway, which is hyperactivated in many different malignancies and is generally linked to a poor prognosis." (PMID 35456975, 2022). "Therefore, strategies combining endocrine therapy or HER2-Neu blockade with IL-6 pathway inhibition would be plausible therapeutic approaches to significantly improve relapse-free survival of patients diagnosed with these breast cancer subtypes." (PMID 35163731, 2022). "Pre-adipocytes showed increased IL-6 secretion and expression of cancer-associated fibroblast (CAF) markers FSP1 and α-SMC and their pathological IL-6 overproduction led to the proliferation and migration of breast cancer cells and xenografts." (PMID 35701840, 2022). "A recent paper discovered that TAMs secrete IL-6 in the TME to stimulate protein arginine methyltransferase 1 (PRMT1)-mediated meR342-EZH2 formation in order to stabilize the enhancer of Zeste Homolog 2 (EZH2) in breast cancer cells." (PMID 35805995, 2022). "In addition, it has been reported that OSM together with IL-1β induces IL-6 in breast cancer cells in culture, and expression of these three factors correlated with low breast cancer patient survival." (PMID 35163731, 2022). "Agents directly targeting the IL-6/IL-6R/gp130 complex for breast cancer therapy." (PMID 35924148, 2022). "Local increases in IL6 could impact the self-renewal of cancer stem cells or potentially the growth of breast cancer cells." (PMID 35087024, 2022). "The FDA has yet to approve IL-6/JAK/STAT3 pathway inhibitors for breast cancer." (PMID 35371975, 2022). "In addition to STAT3, IL-6 can be further activated through nuclear factor kappa B (NF-κB) signaling in breast cancer." (PMID 35371975, 2022). "It is possible that the anti-IL-6-mAb administered to breast cancer patients undergoing CAR-T-cell therapy to manage their cytokine storm may inadvertently have unexpected metastasis-promoting effects." (PMID 35406728, 2022). "The cytokine interleukin-6 (IL6) and its downstream effector STAT3 form a major oncogenic pathway in breast cancer that has been hypothesized to be functionally linked to estrogen receptor (ER)." (PMID 36056349, 2022). "IL-6 could upregulate circulating VEGF in breast cancer patients, which was confirmed to promote angiogenesis and metastasis." (PMID 35924148, 2022). "Among them, IL-6 is critical for STAT3 activation in human breast cancer." (PMID 36009550, 2022). "Moreover, IL-6 also likely contributes to the dysregulated hepcidin/ferroportin signaling in breast cancer and mediates further iron homeostasis." (PMID 35281097, 2022). "Moreover, NF-ƙB expression was positively correlated with PTX-3, PCT, CRP, and IL-6 in patients with breast cancer and colon cancer." (PMID 36499628, 2022).
breast cancer (continued). "Doxorubicin at 100 nM can induce senescence in MDA-MB-231 breast cancer cells, and the SASPs of the senescent breast cancer cells include interleukin-6 (IL-6), IL-8, matrix metalloprotease-1 (MMP-1), IL-1α, and granulocyte-macrophage colony-stimulating factor (GM-CSF)." (PMID 36291773, 2022). "This analysis of seven inflammatory biomarkers and breast cancer risk in a case–control study in premenopausal women from Latin America showed that IL-6 and TNF-α were positively associated with breast cancer risk when accounting for adiposity and other breast cancer risk factors." (PMID 35948877, 2022). "Whether IL-6 mediates organ-specific breast cancer metastasis remains to be conclusively elucidated." (PMID 35371975, 2022). "Therefore, our findings suggest that tumor activated macrophage derived IL-6 regulates CSC phenotype in breast cancer cells." (PMID 35300689, 2022). "In summary, our results demonstrate that TNBC cells but not HR+ cells induce a distinct population of M2-like TAMs that express M1-associated genes and secrete a considerable amount of IL-10 and IL-6, which in turn promotes breast cancer cell proliferation and metastasis." (PMID 35960749, 2022). "For example, it has been illustrated that pro-inflammatory cytokine interleukin (IL)-6 potently stimulates JAK/STAT signaling in breast cancer cell lines, and it has also been shown that both IL-6 and JAK/STAT signaling can potentiate MCL1 transcription in multiple cancer subtypes." (PMID 35349392, 2022). "Involvement of IL-6 in breast cancer has been extensively reported over the years." (PMID 35163731, 2022). "Moreover, in murine models of melanoma, colon cancer and breast cancer, the cytokines IL-6 and IL-8 attracted circulating tumor cells (CTCs) and enhanced metastasis to mammary tissue." (PMID 35769460, 2022). "Recent reports extensively elaborate on IL-6’s pleiotropic effects and pro-metastatic role in breast cancer; however, current evidence on whether IL-6 promotes site-specific metastases requires further investigation." (PMID 35371975, 2022). "The data suggests that treatment with CM of activated macrophage significantly induced the breast cancer cell mediated angiogenesis (1.7-fold increase in tube junction vs control) and the effect was attenuated upon IL-6 neutralization (1.2-fold) or Stattic treatment (1.1-fold)." (PMID 35300689, 2022). "Moreover, only few studies have explored the role of TAM derived IL-6 in regulation of CSCs specifically in breast cancer." (PMID 35300689, 2022). "IL-6 is often detected at increased levels in breast cancer patients." (PMID 35565306, 2022). "In particular, the IL-6/STAT3 pathway was found to be preferentially active in CD44+CD24− breast cancer cells, which have stem-cell-like characteristics, compared with other tumor cell types, and the inhibition of JAK2 decreased their number and blocked the growth of xenografts." (PMID 36010693, 2022). "Thus, our results indicate that IL-6- and IL-10-mediated neutrophil N2 conversion is a key mechanism to promote lung metastasis of breast cancer in the context of Lin28B expression." (PMID 35173168, 2022). "Furthermore, miR-146b inhibits NF-κB-mediated production of IL-6, a proinflammatory cytokine associated with cancer, STAT3 activity, and IL-6/STAT3-driven breast cancer cells migration and invasion." (PMID 36359024, 2022). "A study on breast cancer patients found a negative association between exercise and IL-6 levels; other meta-analyses have also shown a significant decrease in IL-6 and CRP levels after exercise intervention." (PMID 36482346, 2022). "In conclusion, the present study revealed, for the first time, the anti-proliferative, apoptotic, anti-migration and EMT inhibition activities of azilsartan against breast cancer cells through modulating NF-kB/IL-6/JAK2/STAT3/MMP9, TWIST/SNAIL/SLUG and apoptosis signaling pathways." (PMID 36431925, 2022).